STAT3 (signal transducer and activator of transcription 3)
Diseases named in the same sentence as STAT3 in open-access papers (continued):
Sharing a sentence is not in itself a finding about the gene and the disease.
cancer (continued). "In vitro experiments revealed that stress hormones downregulated HDC expression, consequently promoting cancer cell proliferation, migration, and invasion via the IL-6/STAT3/S100A9 pathway." (PMID 39720595, 2024). "Napabucasin (BBI608), an orally administered STAT3 inhibitor, has undergone clinical evaluation for treating various cancers." (PMID 39659524, 2024). "Recently, interest in understanding the importance of the PKM2/STAT3 pathway in the advancement of cancer has increased." (PMID 39411137, 2024). "Stat3 protein is a major regulator of key markers and activators of most cancers, including cell proliferation and response to DNA damage." (PMID 39173044, 2024). "This shows that endogenous OPG can enhance pro-carcinogenic features in both cancer and stromal cells by activating the STAT3/IL-6 pathway." (PMID 39181873, 2024). "Signal transducer and activator of transcription 3 (STAT3) is currently recognized as an oncogene, and in nearly 70% of cancers, abnormal regulation of STAT3 has been confirmed." (PMID 38474604, 2024). "Abnormal expression of NF-κB and STAT3, which are closely related to inflammation and metabolic abnormalities in cancer cells, can affect crucial processes such as glucose metabolism, lipid metabolism, and amino acid metabolism." (PMID 38962132, 2024). "The transcription factor signal transducer and activator of transcription-3 (STAT3) is a central regulator of metastasis and is known to regulate genes that are involved in cancer and wound healing." (PMID 38630692, 2024). "SFN in combination with chemotherapeutic agents was found to regulate MAPK, Akt/mTOR, NF-κB, Wnt/β-catenin, and STAT3 signaling cascades, thereby inducing the reversal of drug resistance in cancer cells." (PMID 38254735, 2024). "CDDO-Me increases sensitivity, decreases resistance to Paclitaxel chemotherapy, and increases apoptosis of cancer cells by reducing STAT3-induced expression of the anti-apoptotic genes in OC cell lines." (PMID 39766086, 2024). "Additional compounds have also been screened to inhibit the transcriptional activity of STAT3 to treat cancer and other diseases." (PMID 39335615, 2024). "Therapeutic implications of targeting the STAT3 pathway in cancer therapy are intriguing due to its potential to promote antitumor effects." (PMID 38397805, 2024). "STAT3, a transcription factor, is known to regulate the transcription of various genes, leading to cancer progression." (PMID 39791720, 2024). "NCAPG2 promotes PCa malignancy and drives cancer stemness via the STAT3/c-MYC signaling axis, highlighting its potential as a therapeutic target for PCa." (PMID 38166947, 2024). "Persistent or dysregulated JAK/STAT3 signaling is involved in many diseases characterized by chronic inflammation and fibrosis, as well as cancer." (PMID 38338677, 2024). "This ultimately leads to phosphorylation of STAT3 at tyrosine 705, whereby STAT3 homodimerizes and translocates to the nucleus to act as a master regulator of cancer-promoting genes." (PMID 38424636, 2024). "For example, persistent activation of STAT3 has been observed in various cancers, including breast, ovarian, and head and neck cancers." (PMID 39353898, 2024). "Several studies have shown that the expression of MMP2/9 is regulated by the STAT3 signaling pathway in a variety of solid tumors, suggesting that increased activation of STAT is the cause of upregulation of MMP2/9 expression in cancer cells." (PMID 38835342, 2024). "Sorafenib prevented cancer expansion in murine GBM xenografts decreasing STAT3 levels and increasing sensitivity towards TTFields." (PMID 38338677, 2024). "Through this IFN-γ-induced STAT3/c-Myc-dependent metabolic switch, cancer cells acquire a metabolic profile distinguished by increased aerobic glycolysis and decreased fatty acid oxidation." (PMID 38791327, 2024).
cancer (continued). "They inhibit the activity of signal transducer and activator of transcription 3 (STAT3) by inhibiting proto-oncogene tyrosine-protein kinase Src kinase phosphorylation, which inhibits the growth and metastasis of cancer cells." (PMID 39063337, 2024). "Recent studies, albeit mostly in cancer research, suggest multiple interactions between STAT3 with different microRNAs." (PMID 37982695, 2024). "For instance, STAT3 inhibition can induce apoptosis and/or activate effective immune responses in colon cancer cells, overcoming cancer-induced immune tolerance." (PMID 38495094, 2024). "A positive feedback loop is created when cancer cells’ overactive STAT3 signaling pathway increases IL-6 synthesis." (PMID 38397437, 2024). "Further analysis showed that inflammatory cytokines (CCL5 and IL-6) derived from the TME are involved in EMT in cancer cells via the STAT3 signaling pathway." (PMID 39126553, 2024). "In this way, many clinical trials regarding STAT3 inhibitors in the context of cancer have failed, necessitating the need for new strategies of targeting STAT3 signaling." (PMID 38464736, 2024). "The universality and ubiquity of STAT3 make it difficult to determine at what stage of cancer development it plays the greatest role." (PMID 39188680, 2024). "STAT3 induces a variety of transcriptional factors that propagate tumorigenesis, including maintaining the cancer stem cell state and invasiveness and upregulation of immunosuppressive factors." (PMID 38254796, 2024). "A pan-cancer analysis combining data from the TCGA and GTEx databases uncovered that STAT3 was significantly highly expressed in only a few tumors, particularly in PCa." (PMID 39132168, 2024). "This work not only provides the binding modes between Stat3 and quercetin, but also contributes to the optimization and design of such anti-cancer inhibitors." (PMID 39173044, 2024). "GL suppressed STAT3-FoxP3 in Tregs and cancer cells, in addition to directly binding to HMGB1, leading to an anticancer effect." (PMID 39150932, 2024). "The combined effect increased cytoplasmic STAT3 actively translocate into the nucleus, which also supported the interdependence of STAT3 tyrosine phosphorylation and serine phosphorylation in different cancer types." (PMID 38596684, 2024). "Other approaches, including inhibitors of Janus kinases (JAKs) and downstream effectors like STAT3 have shown potential in preclinical and clinical studies for the treatment of various cancers." (PMID 39451730, 2024). "Chronic inflammation plays a crucial role in cancer initiation and progression, mediated by pathways such as NF-κB and STAT3." (PMID 39682667, 2024). "STAT3 activates RhoA, an important actin regulator that drives amoeboid movement in many cancer cells, and JAK/STAT3 inhibition decreases migration of malignant cells as evaluated in 3D collagen gels." (PMID 38339245, 2024). "Further experiments revealed that the PI3K-AKT and STAT-3 signaling pathways are involved in the 5-MTP-induced sensitivity of cancer cells to sorafenib." (PMID 38388902, 2024). "Accordingly, simultaneously disrupting the STAT3 signaling, and targeted therapy, would be more promising and effective than monotherapy in human cancers." (PMID 38245798, 2024). "Numerous findings have demonstrated the pivotal function of STAT3 in developing cancer, rendering it a prime candidate for cancer treatment." (PMID 38397437, 2024). "Maintenance of cancer stemness by miR-196b-5p contributes to the chemoresistance of CRC cells via activating the STAT3 signaling pathway." (PMID 38541123, 2024).
cancer (continued). "Luteolin inhibited phosphorylation of STAT3.In vivo studies have proven that luteolin restrained cancer growth and Src/STAT3 signaling." (PMID 38474604, 2024). "STAT3 overexpression enhances cancer cell survival, proliferation, apoptosis resistance, migration, invasion, angiogenesis, immunosuppression, and the self-renewal and differentiation of stem cells by controlling the expression of its downstream target genes." (PMID 39684626, 2024). "For example, we previously showed that genes in an inflammatory network mediated by the joint action of NF-kb, STAT3, and AP-1 transcription factors are coexpressed and the regulatory module is commonly active in many cancer types." (PMID 39041189, 2024). "Given the significant role of IL-6 in the constitutive activation of STAT3, some therapeutic approaches to downregulate the IL-6 signaling pathway have become targets for the therapies of various types of cancer." (PMID 38256080, 2024). "STAT3 also impacts other components of the TME such as the phenotype of fibroblasts, especially those associated with malignant tumors." (PMID 38464736, 2024). "AM-18002 exerted its anticancer effect by inhibiting MDSC expansion and decreasing the invasion and migration of cancer cells, which was related to the suppression of STAT3 phosphorylation." (PMID 38625901, 2024). "In vitro and animal studies reveal that curcumin can inhibit Stat3, a protein crucial for cancer cell growth and survival." (PMID 39816400, 2024). "Signaling by the IL-6/JAK/STAT3 axis is prominent in many human cancers and regulates various cellular functions relevant to cancer advancement, such as inflammation, cell survival, and proliferation." (PMID 38979413, 2024). "In this study, we leverage isogenic STAT3 intact and deficient cells to more fully delineate the effects of STAT3 on oncogenic KRAS dependency and the growth of cancer cells in culture or as tumors." (PMID 38573819, 2024). "The most suitable target for decreasing cytokine-induced cancer cell proliferation is STAT3 activation." (PMID 38256080, 2024). "The activation of EGFR signaling was linked to various cancer development, such as lung cancer and glioma, through its downstream signaling crosstalk with the MAPK, Akt, STAT3 and PKC signaling pathways." (PMID 39451518, 2024). "Consistent results were obtained in cells with FGFR1 knockdown, indicating that simultaneous inhibition of FGFR1/STAT3 signaling greatly promotes the anti-cancer activity of Erdafitinib." (PMID 39247610, 2024). "STAT3 (Signal transducer and activator of transcription 3), a DNA-binding transcription factor and a site of convergence for the majority of initiated oncogenic pathways, plays a role in the pathogenesis of cancers, including apoptosis and metastasis." (PMID 38182570, 2024). "The activated IL-6/STAT3 pathway can inhibit caspase-dependent apoptosis, promoting proliferation and metastasis of cancer cells." (PMID 38673967, 2024). "By inhibiting pro-survival and pro-inflammatory signaling cascades such as PI3K/Akt/mTOR, MAPK, Wnt/β-catenin, NF-κB, Hedgehog, Notch, and JAK/STAT3, curcumin effectively impedes cancer cell growth and promotes apoptosis." (PMID 39507759, 2024). "To validate our findings, we recruited a cohort of 21 cancer patients for histological confirmation, revealing significant mRNA upregulation of STAT3, IL6, MMP9, MMP3, TGFB1, VEGF and HIF1A, coupled with downregulation of LHPP and PCK1, PTEN and BLC2." (PMID 39468431, 2024). "The other important cancer-promoting transcription factor STAT3 was upregulated at the mRNA level and activated at the protein level, confirming the induction of a strong pro-inflammatory response in primary mammary fibroblasts." (PMID 39451241, 2024). "Stat3 belongs to an important intracellular signaling pathway, and its continuous activation is closely related to the occurrence and development of cancer, the present work proposes a possible inhibitory mechanism of quercetin against Stat3." (PMID 39173044, 2024).
cancer (continued). "Further investigation by Jian Wang revealed that in PTEN-deficient cancer cells, a deficiency in PTEN is positively correlated with low STAT3 activity, likely due to hyperactivation of the PI3K/AKT/mTOR pathway." (PMID 39309860, 2024). "OSRE also interact with key oncogenic signaling pathways, including Wnt/β-catenin and JAK2/STAT3, linking them to cancer aggressiveness and therapeutic resistance." (PMID 39594421, 2024). "Signal transducers and activators of transcription 3 (STAT3) is involved in multiple cancers and inflammation." (PMID 39542733, 2024). "So, to check the activity of DiMeOC-Mg-BCD on cancer cell lines at the molecular level, the IL-6/STAT3 signaling pathway was investigated." (PMID 38673967, 2024). "STAT3, which is closely correlated with cancer, can regulate downstream genes to induce proliferation and inhibit apoptosis of cancer cells." (PMID 39174877, 2024). "Inhibition of the STAT3 signaling cascade has been shown to impede the proliferation and metastasis of certain cancers." (PMID 39456642, 2024). "They reported that NP can highly effectively suppress many cancer metastases and recurrences through inhibiting Stat3 gene transcription." (PMID 39356934, 2024). "HCC cell‐secreted exosomal PSMA5 knockdown hinders M2 polarization to suppress cancer progression by restraining JAK2/STAT3 signaling." (PMID 38415977, 2024). "Phosphorylated STAT3 then formed a dimer and entered the nucleus to regulate a variety of target genes involved in cancer growth." (PMID 39153914, 2024). "Signal transducer and activator of transcription 3 (STAT3) is an oncogene that is aberrantly activated in about 70 % of cancers, promoting continuous transcription of growth factors and anti-apoptotic molecules for cell survival." (PMID 39104501, 2024). "Chalcone has been considered a potential molecular strategy for cancer prevention and treatment by targeting STAT3." (PMID 38686052, 2024). "Large-scale analysis of patient-derived PDACs (n=84) and pancreatic cell lines from the Cancer Cell Line Encyclopedia (n=39) reveal low to medium levels of STAT3 Y705 phosphorylation." (PMID 38573819, 2024). "Acting downstream of multiple kinases and growth factor receptors, including but not limited to PDGFR, EGFR and IL-6, STAT3 is an important mediator of gliomagenesis through its role in modulating cancer cell survival, invasiveness, and immune evasion." (PMID 38615034, 2024). "In normal skin tissues, STAT3 promotes wound healing through cell migration, which cancer cells take advantage of as seen with the migration of ovarian cancer cells." (PMID 38464736, 2024). "The target genes directly modulated by STAT transcription factors have been increasingly defined, particularly those regulated by STAT3 in cancer cells." (PMID 38611065, 2024). "It has been known that STAT3 and p300 can contribute to various cancer progression, and STAT3 activation (e.g., p-STAT3) can co-localize with MMP1, governing MMP1 induction in NSCLC." (PMID 38560562, 2024). "Several cancers, including CC, have been shown to activate the IL-6/STAT3 signaling pathway to support cancer cell survival and invasive expansion." (PMID 38511067, 2024). "STAT3 is a critical player in cancer biology, particularly in GBM, where it influencesinvasion, cell cycle regulation, and immune system resistance." (PMID 38716541, 2024). "In fact, the outcomes of NF-κB and STAT3 activation can be highly context-dependent, not only because they are heterogeneously dysregulated in cancers, but also due to their complex crosstalk with various signalings." (PMID 38926796, 2024). "CK2 affects the phosphorylation levels of STAT3 and other components, impacting cancer cell survival." (PMID 38474160, 2024). "Alteration of the STAT3 pathway is one of the aberrant signalling pathways contributing to the hallmarks of cancer." (PMID 38535967, 2024).
cancer (continued). "Constitutive activation and overexpression of STAT3 have been reported in nearly 70% of cancers and are responsible for maintaining cell growth, migration, proliferation, metastasis, and survival." (PMID 39305962, 2024). "Both NF-κB and STAT3 are indispensable for cancer development and progression in gastric, liver and colon cancers." (PMID 39451518, 2024). "EMT type III, EMT associated with metastasis, is an important event in the evolution of cancer that is induced by a set of signaling molecules, such as STAT3 and NF-κB, and signaling cell (M2-TAM)." (PMID 39061137, 2024). "NO can upregulate Notch signaling and IL-6 signaling in tumor cells, leading to prolonged STAT3 activation and promoting cancer cell stemness." (PMID 38254796, 2024). "The inappropriate function of essentially each STAT family member, particularly STAT3 and STAT5, has been associated with human cancer." (PMID 38611065, 2024). "The JAK2/STAT3 signaling pathway is crucial in cancer development, involved in processes like immune regulation, angiogenesis, cell proliferation, and differentiation." (PMID 39781272, 2024). "STAT3 is a key regulator of cancer-related inflammation and is frequently activated in malignant cells." (PMID 39309860, 2024). "We aim to delineate the role of STAT3 in shaping the patterns of oncogenic KRAS dependency in KRAS mutant cancer cells." (PMID 38573819, 2024). "In conclusion, targeting the STAT3 and NF-κB signaling pathways in cancer prevention and treatment holds great promise, and chalcones have emerged as potential therapeutic agents in this regard." (PMID 38539427, 2024). "STAT3, a downstream IL6 effector, is activated in most cancers, including OC, and has been linked to aggressive OC clinical behavior." (PMID 39766086, 2024). "Studies have demonstrated that some members of the STAT family, such as STAT3, control the activation of genes related to cell growth, formation of new blood vessels, and the spread of cancer cells." (PMID 39353898, 2024). "Although numerous studies have focused on suppressing STAT3 as a potential cancer treatment, it is hard to develop an inhibitor directly targeting STAT3." (PMID 39202965, 2024). "Due to the activation of STAT3 frequently occurred in many human cancers, and it was correlated with the malignant properties of cancers." (PMID 38342622, 2024). "In PI3K-activated cancers, p27pTpT plays a transcriptional regulatory role to co-activate STAT3 and cJun to govern gene programs critical for CSC self-renewal." (PMID 38886396, 2024). "Next, we analysed the functional effects of the interaction between PRMT5 and STAT3 in cancer cells." (PMID 38760429, 2024). "There is mounting evidence indicating the collaborative role of STAT3 and NF-κB in advancing the onset and progression of diverse cancers." (PMID 38856747, 2024). "TAARD is a synthetic derivative of diphyllin that promotes levels of TLR1 in NF-κB phosphorylation while it increases TLR3 expression in STAT3 phosphorylation to promote IFN-γ levels in potentiating function of NK cells in cancer therapy." (PMID 39014491, 2024). "As STAT3 is recognized as a potential therapeutic target in cancer, the inhibition of its signaling is explored to induce apoptosis and overcome resistance to cell death." (PMID 39594587, 2024). "Natural compounds have been widely used in cancer treatment due to their low toxicity and low carcinogenesis rate, some of which act on the Stat3 target." (PMID 39173044, 2024). "Another study also revealed that saikosaponin D exerted anti-cancer effect against HCC by suppressing COX-2 via inhibiting p-STAT3/CCAAT enhancer binding protein beta (C/EBPβ) pathway." (PMID 39354529, 2024). "NP, known for its role in inhibiting cancer stem cell pathways, and DX, a widely used chemotherapeutic agent, were observed to decrease Stat3 activity, leading to reduced expression of downstream oncogenic targets." (PMID 39356934, 2024).